TUG1 (taurine up-regulated 1)
Diseases named in the same sentence as TUG1 in open-access papers (continued):
Sharing a sentence is not in itself a finding about the gene and the disease.
bladder urothelial carcinoma (9 papers, 2015 to 2022). "TUG1 is another lncRNA whose aberrant overexpression is commonly linked to urothelial carcinoma of the bladder, as well as to B-cell malignancies, esophageal squamous cell carcinoma, hepatocellular carcinoma and osteosarcoma." (PMID 29165379, 2017). "Studies on human cancers have concluded that TUG1 is overexpressed in urothelial carcinoma of the bladder and is associated with high-grade and advanced-stage diseases." (PMID 27485439, 2016). "In human cancers, TUG1 has been reported to be associated with urothelial carcinoma of the bladder, osteosarcoma, esophageal squamous cell carcinoma, and NSCLC." (PMID 27485439, 2016). "Taurine-upregulated gene 1 (TUG1) is upregulated in bladder urothelial carcinoma and it promotes proliferation and migration of ESCC cells." (PMID 35327559, 2022). "Up-regulation of lncRNA TUG1 expression in bladder urothelial carcinoma inducing by transcription factor Nrf2 promoted cancer progression and adriamycin resistance." (PMID 34039257, 2021). "And the TF Nrf2 promotes the occurrence and development of bladder urothelial carcinoma by interacting with TUG1." (PMID 34721660, 2021). "Further studies are needed to better understand the importance of TUG1, though its potential roles as biomarker and therapeutic target in bladder urothelial carcinoma seem to be well established." (PMID 29165379, 2017). "TUG1 expression is also elevated in Huntington's disease as well as urothelial carcinoma of the bladder and successful knockdown of TUG1 with siRNAs has been reported." (PMID 26578588, 2016). "Inhibition of cell proliferation and induction of apoptosis were observed in TUG1 knockdown bladder urothelial carcinoma T24 and 5637 cells." (PMID 27485439, 2016).
colon cancer (9 papers, 2017 to 2023). "In ovarian cancer cells, lncRNA taurine upregulated 1 (TUG1) overexpression has been implicated in the promotion of cellular proliferation and inhibition of apoptosis, suggesting its plausible involvement to also mediate tumorigenesis and chemoresistance in colon cancer cells." (PMID 34571731, 2021). "Higher taurine-upregulated gene 1 (TUG1) expression has been reported in colon cancer tissues, and p63 downregulation increases TUG1 expression in HCT116 and LoVo colon cancer cells." (PMID 33246471, 2020). "Indeed, the knockdown of TUG1 has demonstrated enhanced 5-FU chemosensitivity via the downregulation of TYMS expression in colon cancer cells." (PMID 34571731, 2021). "Similarly, another study identified that knockdown of TUG1 blocks the proliferation of colon cancer cells, and impedes tumor growth in vivo." (PMID 33246471, 2020). "The results of this study suggest that TUG1 facilitates EMT in colon cancer cells." (PMID 33246471, 2020). "It is found that overexpression of lncRNA TUG1 promotes colon cancer progression." (PMID 31572428, 2019). "However, existing studies report TUG1 should be significantly upregulated in T and cell line experiments then documented that TUG1 promotes cell proliferation and colon cancer cell migration." (PMID 30205577, 2018). "Inhibition of TUG1 expression blocked the cell migration ability of colon cancer cells." (PMID 28108736, 2017). "Firstly, we obtained 558 transcription factors that had potential interactions with lncRNA TUG1 through the RNA Interactome Database and obtained the top 100 elevated genes in the COAD colon cancer database (GEPIA2)." (PMID 34858502, 2021). "Downregulation of TUG1 was shown to suppress EMT in part by targeting miR-26a-5p and MMP-14, VEGF, MAPK and Hsp27 in colon cancer cells." (PMID 33246471, 2020). "Mechanistically, TUG1 overexpression elevates p-p38 mitogen-activated protein kinase (p-p38 MAPK), and p-heat shock protein 27 (p-Hsp27) levels in colon cancer." (PMID 33246471, 2020). "In addition, knockdown of TUG1 expression has been shown to attenuate the migration of HCT116 and LoVo colon cancer cells." (PMID 33246471, 2020). "Moreover, the oncogenic lncRNA TUG1 inhibits the apoptosis of HCT116 and LoVo colon cancer cells." (PMID 33246471, 2020).
myocardial infarction (9 papers, 2019 to 2025). Gross necrosis of the myocardium, as a result of interruption of the blood supply to the area, as in coronary thrombosis. "Recent studies have found that TUG1 is involved in the development of several cardiovascular diseases, including aortic valve calcification, myocardial ischemia–reperfusion injury, myocardial infarction, and other cardiovascular diseases." (PMID 34540908, 2021). "On the one hand, TUG1 can inhibit apoptosis in hypoxia-induced injury of H9c2 cell, thereby reducing hypoxia-induced cell damage and inhibiting myocardial infarction." (PMID 33879068, 2021). "Furthermore, lncRNA TUG1 has been identified as a potential therapeutic target following myocardial infarction." (PMID 40162308, 2025). "Similarly, TUG1 was upregulated in ischemic heart and cardiomyocytes while knockdown of TUG1 inhibited cardiomyocyte apoptosis and markedly ameliorated impaired cardiac function of myocardial infarction mice by upregulating miR-9 expression." (PMID 34429073, 2021). "In a recent study, TUG1 is reported to be induced in ischemia challenged cardiomyocytes, and downregulation of TUG1 may be a new target against the injury of acute myocardial infarction (AMI)." (PMID 34540908, 2021). "I/R-induced TUG1 binds to miR-132-3p to activate histone deacetylase 3 and then provokes intracellular reactive oxygen species accumulation, and worsens the injury of acute myocardial infarction." (PMID 34429073, 2021).
osteoarthritis (7 papers, 2020 to 2025). A noninflammatory degenerative joint disease occurring chiefly in older persons, characterized by degeneration of the articular cartilage, hypertrophy of bone at the margins and changes in the synovial membrane. "Furthermore, TUG1 is associated with poor prognosis for osteoarthritis patients, and the elevated expression of this lncRNA promotes osteoarthritis-induced degradation of chondrocyte extracellular matrix via the miR-195/MMP-13 axis." (PMID 32791451, 2020). "Taken together, lncRNA TUG1 could be associated with osteoarthritis pathogenesis." (PMID 37779916, 2023). "This study elucidated the role of the TUG1/miR‐144‐3p/DUSP1/p38 MAPK regulatory network in osteoarthritis chondrocyte injury." (PMID 40067024, 2025). "LncRNA taurine upregulated gene 1 (TUG1) has been found to be elevated in cartilages of osteoarthritis patients compared with normal cartilages." (PMID 37779916, 2023). "Silencing of TUG1 repressed osteoarthritis progression via downregulation of FUT1 by inhibition of miR-17–5p, which was due to promotion of viability and inhibition of apoptosis and ECM degradation in chondrocytes." (PMID 37779916, 2023). "Our study further identifies a role for TUG1 in regulating cartilage damage in osteoarthritis and correlates it with the MAPK pathway." (PMID 37340458, 2023). "Secondly, besides playing the function of ceRNA, whether TUG1 is involved in regulating the progression of osteoarthritis through other functions." (PMID 37340458, 2023). "Firstly, we only explored the molecular mechanism of TUG1 as ceRNA sponging miR-144-3p; however, whether TUG1 can act as ceRNA to affect the expression of other key regulators in osteoarthritis needs to be further investigated." (PMID 37340458, 2023). "In addition, one study revealed that lncRNA TUG1 governed ECM degradation of chondrocytes in osteoarthritis via control of miR-320c/MMP-13 pathway." (PMID 37779916, 2023). "In our study, we examined the TUG1 expression in primary OA chondrocytes and C28/I2 cells by combining expression data from the GEO database and bioinformatics analysis and found that TUG1 is under-expressed in osteoarthritis and shows a close correlation with the P38 MAPK signaling pathway." (PMID 37340458, 2023).
acute myeloid leukemia (6 papers, 2021 to 2024). Acute myeloid leukemia (AML) is a group of neoplasms arising from precursor cells committed to the myeloid cell-line differentiation. "For instance, lncRNA TUG1 was upregulated in ADR (Adriamycin)-resistant AML (acute myelocytic leukemia) tissues and cells, and high expression of TUG1 was correlated with poor prognosis of AML patients." (PMID 34980123, 2022). "The glycolysis process of acute myelogenous leukemia was affected by lncRNA TUG1 to promote cancer growth." (PMID 34039257, 2021). "In addition, ‘PI3K-Akt signaling pathway’42, ‘cell cycle’43, ‘acute myeloid leukemia’44 and ‘Insulin signaling pathway’45 pathways have been experimentally confirmed to be related with TUG1." (PMID 35322118, 2022). "lncRNA TUG1 was up-regulated in acute myeloid leukemia (AML) patients and cells, and lncRNA TUG1 promoted the proliferation and glycolysis of AML cells by targeting miR-185." (PMID 34039257, 2021). "In addition, TUG1 expression was elevated in refractory or relapsed acute myeloid leukemia (R/R AML) patients who received Ara-C combined with other drugs." (PMID 36532760, 2022). "It has been reported that TUG1 can activate the MAPK1/ERK pathway through the ceRNA network, which is crucial for the pathogenesis of acute myeloid leukemia." (PMID 37303492, 2022). "Although the precise mechanism by which TUG1 regulates AURKA in HCC was not demonstrated in the study, consistent evidence showed that TUG1 positively modulates AURKA in adult acute myeloid leukemia (AML)." (PMID 39598228, 2024).
cardiac hypertrophy (6 papers, 2020 to 2023). "Herein, we identified the functional role and the underlying mechanisms of TUG1 in cardiac hypertrophy." (PMID 33817315, 2021). "Silencing TUG1 is also suggested to inhibit cardiac hypertrophy, which is considered to be the major risk factor for the occurrence of AF." (PMID 34540908, 2021). "To further investigate the functional role of TUG1 in cardiac hypertrophy, we performed loss-of-function experiments with si-TUG1." (PMID 33817315, 2021). "The current study was designed to explore the role and underlying mechanism of lncRNA taurine up‐regulated gene 1 (TUG1) in cardiac hypertrophy." (PMID 32057178, 2020). "We, therefore, wandered to explore the role and underlying mechanism of TUG1 in cardiac hypertrophy." (PMID 32057178, 2020). "In addition, TUG1 knockdown is also suggested to attenuate AngII-induced cardiac hypertrophy, which is considered to be the major risk factor for the occurrence of AF." (PMID 34540908, 2021). "Knockdown of TUG1 mitigated cardiac hypertrophy and decreased cardiac fibrosis in vivo, and attenuated the hypertrophic response in cardiomyocytes treated with high glucose in vitro." (PMID 38259314, 2023). "In summary, lncRNA TUG1 emerges as a multifaceted regulator with potential implications in both cardiac hypertrophy and fibrosis, suggesting its potential as a driver for HFpEF pathogenesis." (PMID 38259314, 2023). "Knockout of taurine upregulated gene 1 (TUG1) suppresses cardiac hypertrophy by sponging miR-29b-3p." (PMID 35139769, 2022). "For example, the lncRNA Plscr4 and lncRNA taurine upregulated gene 1 (TUG1) has been shown to regulate cardiac hypertrophy seemingly through regulation of miR-214 and miR-29b-3p, respectively." (PMID 36429092, 2022). "The aim of this study was to investigate the detailed role and molecular mechanism of long noncoding RNA (lncRNA) taurine upregulated gene 1 (TUG1) in cardiac hypertrophy." (PMID 33817315, 2021). "A recent study demonstrated that taurine upregulated gene 1 (TUG1) was involved in the pathogenesis of cardiac hypertrophy by sponging miRNA-29b-3p." (PMID 33817315, 2021). "To investigate the involvement of TUG1 in cardiac hypertrophy, we first established the cardiac hypertrophy model by TAC in vivo and Ang II treatment in vitro." (PMID 33817315, 2021). "In a study of cardiac hypertrophy, TUG1 is reported to be a positive modulator of cardiac hypertrophy via sponging miR-29b-3p." (PMID 34540908, 2021). "In the study of cardiac hypertrophy, TUG1 is identified to inhibit the expression of miR-29b-3p, and TUG1 contributes to cardiac hypertrophy via sponging miR-29b-3p." (PMID 34540908, 2021). "To further understand the function of TUG1 in cardiac hypertrophy, we used online database LncBase Predicted v.2 to help identify the miRNAs that potentially bind to TUG1." (PMID 33817315, 2021). "All of these results indicated that TUG1 overexpression alleviated TAC‐induced cardiac hypertrophy and dysfunction through TUG1/miR‐34a/DKK1/Wnt‐β‐catenin signalling in vivo." (PMID 32057178, 2020). "Next, we will build heart‐specific mice to overexpress or knockout TUG1 expression, further confirming the role of TUG1 on cardiac hypertrophy." (PMID 32057178, 2020). "The increased expression of TUG1 was not enough to counteract the pro‐hypertrophy effect of miR‐34a, therefore causing cardiac hypertrophy." (PMID 32057178, 2020). "Therefore, in this study, we just focused on the early molecular mechanisms of TUG1, while the role of TUG1 overexpression in the later period of cardiac hypertrophy cannot be concluded." (PMID 32057178, 2020). "Besides regulating cardiac hypertrophy which we have just reported, TUG1 is also reported to mediate cardiac injury." (PMID 32057178, 2020). "In conclusion, the current study reported the protective role and regulatory mechanism of TUG1 in cardiac hypertrophy and suggested that TUG1 may serve as a novel molecular target for treating cardiac hypertrophy." (PMID 32057178, 2020).
cardiac hypertrophy (continued). "Functionally, overexpression of TUG1 alleviated cardiac hypertrophy both in vivo and in vitro." (PMID 32057178, 2020). "We proposed that, in the initial period of cardiac hypertrophy, TUG1 up‐regulation may be an adaptive response to partially offset the increase of miR‐34a which promoted cardiac hypertrophy, leading to adaptively hypertrophic growth of cardiomyocytes." (PMID 32057178, 2020). "However, the effect of interplay between TUG1 and miR-497 in cardiac hypertrophy remains undefined." (PMID 33817315, 2021). "In conclusion, our research revealed TUG1 targeted miR‐34a to block the inhibitory effects of miR‐34a on DKK1, thereby inhibiting the activation of Wnt/β‐catenin signalling and alleviating cardiac hypertrophy." (PMID 32057178, 2020). "Knockdown of TUG1 rescued Ang II-induced hypertrophy in cardiomyocytes at least partly through targeting the miR-497/MEF2C axis, highlighting a novel promising therapeutic target for cardiac hypertrophy treatment." (PMID 33817315, 2021).
Huntington disease (6 papers, 2012 to 2021). Huntington disease (HD) is a rare neurodegenerative disorder of the central nervous system characterized by unwanted choreatic movements, behavioral and psychiatric disturbances and dementia. "Up-regulation of TUG1 is associated with the pathogenesis of Huntington's disease, which is a neurodegenerative disease." (PMID 34621163, 2021). "Taurine up-regulated 1 (TUG1) is known to be involved in neurological disorders including Huntington’s disease." (PMID 29653596, 2018). "In humans, elevated levels of TUG1 have been found in the caudate nucleus of patients suffering from Huntington's disease, whereas additional studies showed that lncRNA TUG1 was involved in cancer progression, affecting apoptosis and proliferation in several human tumor cells." (PMID 27148353, 2016). "Recently it was found that repression of HAR1F by REST leads to its decreased expression in the striatum of Huntington’s disease, and that REST also interacts with DGCR5 and TUG1 lncRNAs leading to DiGeorge syndrome and Huntington’s disease." (PMID 22811697, 2012). "Johnson (2012) extended these investigations and confirmed that both TUG1 and NEAT1 are significantly up-regulated in Huntington’s disease brains, whereas MEG3 and DGCR5 showed decreased expression." (PMID 22811697, 2012).
hyperlipidemia (6 papers, 2019 to 2023). "The inflammatory response reported that a TUG1 knockdown occurred, associated with a decrease in hyperlipidemia and a decrease in the release of inflammatory cytokines, and lncRNA TUG1 was upregulated in LPS-induced hepatocyte inflammation by targeting miR140-TNF." (PMID 37736902, 2023). "Taurin-up-regulated gene 1 (TUG1) knockdown prevents hyperlipidemia and atherosclerotic lesions through up-regulating the miR-133a expression which targets the fibroblast growth factor 1 (FGF1)." (PMID 34552965, 2021). "It was suggested that TUG1 promoted hyperlipidemia and inflammatory cytokines such as IL-6 and TNF-α by sponging miR-133a, which targeted the fibroblast growth factor 1 (FGF1) in ox-LDL-treated RAW264.7 cells." (PMID 32082313, 2020). "MiR-26a was also found to attenuate hyperlipidemia and the inflammatory response in vivo, suggesting the TUG1 might play an important role in cholesterol efflux and inflammation by regulating of miR-26a." (PMID 32082313, 2020). "However, TUG1 promoted hyperlipidemia and inflammatory cytokines such as IL-6 and TNF-α via sponging miR-133a." (PMID 32082313, 2020).
ischemia (6 papers, 2013 to 2022). A hypoperfusion of the BLOOD through an organ or tissue caused by a PATHOLOGIC CONSTRICTION or obstruction of its BLOOD VESSELS, or an absence of BLOOD CIRCULATION. "Our previous findings showed that the expression of TUG1 was elevated during ischemia, and silencing TUG1 expression alleviated cardiomyocyte injury via inhibition of ROS." (PMID 35396503, 2022). "Long noncoding RNA (lncRNA) taurine upregulated gene 1 (TUG1) is increased under the condition of ischemia." (PMID 34429073, 2021). "Therefore, the TUG1/miR-204-5p/COX2 axis was involved in ischemia and reperfusion-induced neuronal damage." (PMID 35228515, 2022). "TUG1 sponged microRNA-9 and promoted neuronal apoptosis by upregulating Bcl2l11 under ischemia." (PMID 35228515, 2022). "MSUR1, 17A, Gadd7 and TUG1, induced by ischemia-related pathological processes, could be modulated by siRNAs to verify their possible role as neuroprotectants." (PMID 24961318, 2013).
lung adenocarcinoma (6 papers, 2014 to 2021). A carcinoma that arises from the lung and is characterized by the presence of malignant glandular epithelial cells. "To examine the relationship between lncRNA perturbators and lncRNA-perturbated mRNAs, we overexpressed lncRNA SNHG7 and TUG1 in the A549 lung adenocarcinoma cell line." (PMID 32846981, 2020). "RNA immunoprecipitation (RIP) and RNA pulldown assays in lung adenocarcinoma cells demonstrated the interaction between TUG1 and the histone methyltransferase EZH2." (PMID 29570632, 2018). "TUG1 aberrant expression in serum samples from lung adenocarcinoma patients compared to healthy donors showed a correlation with tumor size, degree of differentiation, metastasis and TNM stage." (PMID 29570632, 2018). "Finally, to examine the relationship between lncRNA perturbators and lncRNA-perturbated mRNAs, we overexpressed lncRNA SNHG7 and TUG1 in the A549 lung adenocarcinoma cell line and experimentally validated their function to remarkably enhance the expression of PNMA2 and CDC7 respectively." (PMID 32846981, 2020).